SIRT1 (sirtuin 1)
Diseases named in the same sentence as SIRT1 in open-access papers (continued):
Sharing a sentence is not in itself a finding about the gene and the disease.
tumor (continued). "Endothelial cells and pericytes exhibit low to moderate expression, with the MGM group again demonstrating a mild elevation, potentially indicating altered SIRT1 activity within the tumor vascular system." (PMID 41208649, 2025). "The upregulated SIRT1 can directly deacetylate NF-κB and inhibit its activity, ultimately achieving the purpose of anti-tumor." (PMID 40567502, 2025). "Post-treatment, tumor weight decreased dose-dependently, with significant differences between wild-type and SIRT1-overexpressing tumors." (PMID 40872615, 2025). "Normally, miR-181a-5p promotes tumorigenesis by inhibiting SIRT1, a gene involved in tumor suppression and cellular homeostasis." (PMID 40781643, 2025). "Our findings revealed that miR-30c-5p suppresses the proliferation and induces apoptosis in the human granulosa-like tumor cell line (KGN) via targeting SIRT1." (PMID 40855144, 2025). "It exerts tumor-suppressive effects by negatively regulating miR-181a-5p, which in turn relieves the inhibition of SIRT1, a gene involved in ferroptosis." (PMID 40781643, 2025). "In endothelial cells, exosomal LYPLAL1-DT enhances angiogenesis by modulating miR-204-5p, PFN2, and SIRT1 levels, underscoring its critical role in tumor progression and vascular remodeling." (PMID 41551597, 2025). "SIRT1 deacetylates the p65 subunit, thereby reducing pro-inflammatory gene expression and restraining chronic inflammation within the tumor microenvironment." (PMID 41008982, 2025). "Recent studies have revealed that SIRT1 not only governs the intracellular redox balance but also plays a key role in shaping the tumor immune microenvironment." (PMID 41008982, 2025). "Activating sirtuin 1 significantly increases the depletion of nicotinamide adenine dinucleotide (NAD+) levels in IDH-mutant tumor cells, which rely heavily on NAD+ for survival." (PMID 40710366, 2025). "Meanwhile, the expression pattern of cytoplasmic SIRT1 was a poor prognostic factor in H2BC, as it was associated with a larger tumor size (p < 0.036)." (PMID 39858444, 2025). "Resveratrol enhances autophagy activity and anti-tumor effects by increasing autophagosome accumulation and modulating the acetylation of SIRT1 and other autophagy-related proteins." (PMID 41213956, 2025). "Reduced activity of CD38 increases the bioavailability of NAD and activates SIRT1, thereby regulating the growth and differentiation of T cells and tumor growth." (PMID 40529366, 2025). "Compared to those cultured with tumor cells from the control group, T cells cocultured with tumor cells from the SIRT1‐OE group exhibited reduced IFN‐γ and TNF‐α production, decreased Ki‐67 expression, and increased PD‐1 expression." (PMID 39783838, 2025). "For example, SIRT1 interacts with menin, a tumor suppressor and transcriptional regulatory protein that controls fatty acid transporter CD36 expression via histone modification." (PMID 40052151, 2025). "This overall pattern further validates the systematic upregulation of SIRT1 in the context of MGM pathology compared to non‐tumor control." (PMID 41208649, 2025). "Compared to conventional finasteran therapy, the targeted-Sirt1 results in lower brain androgen levels and smaller tumor volumes." (PMID 40075208, 2025). "Conversely, NMN, an NAD+ precursor that activates SIRT1, increased tumor growth and PD‐L1 expression." (PMID 39988985, 2025).
tumor (continued). "This upregulation is partly driven by HPV16 E7, which boosts SIRT1 protein levels and promotes tumor proliferation, invasion, and survival." (PMID 41471349, 2025). "Both genetic overexpression of SIRT1 and the use of pharmacological SIRT1-activating compounds inhibit the growth of IDH1-mutant tumor cells." (PMID 40710366, 2025). "Among these, SIRT1 is the most extensively studied and has been suggested both as a tumor promoter and contributor of therapy resistance." (PMID 41471349, 2025). "Initially identified as a tumor promoter due to its capability to downregulate multiple anticancer factors, recent evidence suggests a dual role for Sirt1, also acting as a tumor suppressor." (PMID 40075208, 2025). "In sorafenib-resistant HCC models, elevated SIRT1 enhances autophagy and NF-κB activation, promoting tumor survival and resistance to treatment." (PMID 40052151, 2025). "SIRT1 plays an important role in the regulation of cellular senescence, energy metabolism, and tumor growth." (PMID 41020376, 2025). "EX-527, a synthetic SIRT1 inhibitor, has been extensively studied for its ability to suppress tumor cell proliferation by modulating SIRT1-mediated pathways, thereby enhancing apoptosis and decreasing cell viability." (PMID 40052151, 2025). "The upregulation of SIRT1 by SRT1720 (SIRT1 activator) attenuates melatonin’s antioxidant and antitumor activity, indicating that its induction of ROS production in tumor cells is activated by SIRT1." (PMID 40650041, 2025). "Plasma SIRT1 levels showed significant correlations with various tumor markers (e.g., CEA, CA199, CA125, CA724)." (PMID 41020376, 2025). "While USP14 overexpression alone is not enough to polarize macrophages, inhibiting USP14 with IU1 can reshape the tumor microenvironment, underscoring SIRT1’s key role in the “cold tumor” phenotype." (PMID 40567502, 2025). "It modulates key processes by inhibiting the PI3K/Akt pathway to suppress ischemic angiogenesis and tumor growth, while activating the SIRT1/Nrf2 pathway to reduce oxidative stress and inflammation." (PMID 40332077, 2025). "Tumor suppressor and oncogenic pathways: In Type I EC, SIRT1 can act as both a tumor suppressor and an oncogene." (PMID 41300302, 2025). "Our current findings have clearly established associations between SIRT1 expression levels and MGM progression as well as tumor immune infiltration." (PMID 41208649, 2025). "Therapeutically, HDAC1 and SIRT1 can be targeted using small-molecule inhibitors that disrupt their enzymatic activity, reversing the epigenetic repression of tumor-suppressive miRNAs, including the miR-449 family." (PMID 41425255, 2025). "Sirt1 is a multifunctional transcription factor involved in the regulation of inflammation, fibrosis, and tumor progression." (PMID 40874461, 2025). "Manipulating H4K16 acetylation levels, influenced by SIRT1 and hMOF, modulates the tumor-supporting functions of microglia." (PMID 40710366, 2025). "Collectively, these findings underscore the therapeutic relevance of targeting HDAC1 and SIRT1 to restore tumor-suppressive miRNA expression and enhance chemosensitivity, providing a mechanistic basis for overcoming resistance in TNBC and other malignancies." (PMID 41425255, 2025). "First, the dual role of SIRT1 as both a tumor promoter and suppressor, depending on the cellular context, complicates its therapeutic application." (PMID 41008982, 2025).
tumor (continued). "Conversely, deacetylation by SIRT1 represses these transcriptional outputs and supports tumor cell survival." (PMID 41008982, 2025). "USP14-mediated SIRT1 stabilization promotes M2 macrophage polarization via SIRT1/PGC1-α-mediated lipid oxidation in mouse tumor models." (PMID 40567502, 2025). "In some contexts, SIRT1 can also act as a tumor suppressor, particularly with regard to regulating apoptosis and DNA repair mechanisms." (PMID 41300302, 2025). "In gastrointestinal cancer, SIRT1 enhances tumor cell survival by promoting redox homeostasis, mitochondrial function, and resistance to metabolic stress." (PMID 41008982, 2025). "Utilizing a tumor xenograft model, astragalus polysaccharides, administered at a dosage of 100 mg/kg, have been shown to exert an inhibitory effect on tumor growth via modulation of the miR-138-5p/SIRT1/SREBP1 signaling pathway." (PMID 39210410, 2024). "Despite evidence suggesting that increased stability and upregulation of SIRT1 can suppress mitophagy and enhance apoptosis, some findings overexpressed SIRT1 can facilitate drug resistance in tumor cells." (PMID 39403142, 2024). "A landmark study offers a pioneering exploration of the complex role of SIRT1 in tumor differentiation and maintenance within the exocrine pancreas, shedding light on mechanisms that hold significant therapeutic promise." (PMID 39682281, 2024). "An integrative network analysis demonstrated that, miR-181/SIRT1 circuit had a regulatory effect on several important metabolic tumor-related processes." (PMID 38598008, 2024). "Elevated NAMPT levels enhance SIRT1-mediated deacetylation and FOXO3a expression, providing protection against oxidative stress and supporting tumor resilience." (PMID 39796040, 2024). "SIRT1 emerges as a pivotal player in orchestrating the immune landscape within the PCa microenvironment, driving immune evasion and tumor progression." (PMID 39796040, 2024). "By modulating critical oncogenic processes such as epithelial–mesenchymal transition via its interactions with the MBD1-Twist-SIRT1 complex, SIRT1 not only influences tumor invasiveness but also impacts chemotherapy sensitivity." (PMID 39682281, 2024). "The dual role of SIRT1 in tumor progression is evident from its effects on tumor cell proliferation, migration, and invasion." (PMID 38044396, 2024). "With respect to SIRT1, significant overexpression of this gene was found in all tumor tissues as compared with normal ones." (PMID 38504782, 2024). "Naged promotes the generation of NETs by activating the histone deacetylase SIRT1 through the tumor-secreted nicotinamide phosphoribosyltransferase (NAMPT), thereby driving tumor metastasis." (PMID 38817858, 2024). "The carcinogenic effect of SIRT1 is mainly manifested in its influence on tumor invasion and migration, and participates in the inhibition of programmed cell death." (PMID 39479446, 2024).
tumor (continued). "Taken together, our findings provide a deep understanding of the molecular mechanism of SIRT1 ISGylation to determine its contribution to tumor progression and the response to therapy." (PMID 38443596, 2024). "These pathways involve NAD-dependent PARPs and SIRT1 enzymes, that are important for the correct DNA repair which prevents the tumor transformation." (PMID 38504052, 2024). "After 28 days, the average tumor volume in the oe-SIRT1 group increased to (1381.01 ± 77.53) mm3, which was significantly larger than that in the control oe-NC group (985.17 ± 75.21) mm3." (PMID 39266959, 2024). "This last model suggested that the tumour suppressive action of SIRT1 must be exerted on Wnt/β-catenin." (PMID 39494323, 2024). "In contrast, the tumor volume in the sh-SIRT1 group was (374.17 ± 39.83) mm3, much smaller than that in the oe-SIRT1 control group (1005.66 ± 108.05) mm3." (PMID 39266959, 2024). "For example, the expression of HDAC2/3/7/10 and SIRT2/3/6/7 associates with tumor size in BRCA, the level of HDAC4/5/8/10/11 and SIRT1/5/7 associates with tumor size in KIRC, and the upregulation of HDAC2/4/6/7 and SIRT1/2/6 associates with tumor size in LUAD." (PMID 39063083, 2024). "This outcome strongly implies that the capacity of aspirin to induce tumor cell apoptosis is contingent upon the presence of the SIRT1 protein." (PMID 38482749, 2024). "Intriguingly, SIRT1 WT complementation facilitated tumor growth and rendered tumors resistant to doxorubicin, whereas SIRT1 KR complementation attenuated tumor growth and sensitized tumors to doxorubicin." (PMID 38443596, 2024). "This is explained by the fact that secondary signal transducers correlated to tumor suppressors (such as SIRT1) or potential oncogens (for example, mTOR, and KRAS) behave pleiotropically depending on the tissue or cell type." (PMID 39203892, 2024). "Resveratrol can induce growth inhibition and apoptosis in tumor cell lines at 70–150 μM and exert beneficial effects in aging models by its pharmacological activation of SIRT1." (PMID 38256903, 2024). "Tumor weight in the sh-SIRT1 group decreased by approximately 60% compared to the sh-NC group, while tumor weight in the oe-SIRT1 group increased by about 50% compared to the oe-NC group." (PMID 39266959, 2024). "The discrepancy in their ability to reduce NAD+ generation led us to explore the role of a tumor-associated NADH oxidase (tNOX, ENOX2) in 4-dmH-suppressed SIRT1 and apoptosis induction." (PMID 38567911, 2024). "Our results strongly support a central role for the miR-181c/d-SIRT1 axis in modulating key components of tumor growth with target therapy resistance both in vitro and BTC clinical sample." (PMID 38598008, 2024). "Sirt1 protein expression was approximately 16% lower in the gastrocnemius of tumor‐bearing mice compared to control mice." (PMID 38946587, 2024). "Another study showed that SIRT1 can inhibit tumor progression by inhibiting the activity of HIF-1α and reducing the ability of KIRC cells to adapt to hypoxic environments." (PMID 39845948, 2024). "It suppressed tumor cell proliferation by inhibiting protein-deacetylating activities of SIRT1 and SIRT234,35." (PMID 38561419, 2024). "Young Joo Jeon at Chungnam National University College of Medicine, Daejon, South Korea, and co-workers found that ISG15 can conjugate to another protein, SIRT1, which also affects tumor growth and response to treatment." (PMID 38443596, 2024). "Tumor growth slowed in the sh-NC and oe-NC groups after drug administration, with the sh-SIRT1 group tumors gradually shrinking, while the oe-SIRT1 group tumors continued to grow rapidly." (PMID 39266959, 2024).
tumor (continued). "Collectively, these findings position SIRT1 as a central mediator in various signaling cascades, influencing tumor progression, metabolism, autophagy, and apoptosis in PCa." (PMID 39796040, 2024). "Beyond its direct effects on autophagy, SIRT1’s regulatory actions extend to other cell death processes, including apoptosis and ferroptosis, thereby influencing tumor cell proliferation, metastasis, and chemotherapy responses." (PMID 39403142, 2024). "Previous studies have reported that overexpression of SIRT1 significantly enhances resistance to cisplatin and paclitaxel in vitro, and overexpression of SIRT1 accelerates the growth of tumor xenografts in nude mice and cisplatin resistance in vivo." (PMID 39266959, 2024). "The elevation of OSBPL3 through the APMK/SIRT1/NF-κB pathway was able to counteract the tumor-suppressing effects of ENST00000534735 overexpression." (PMID 39403142, 2024). "Immunohistochemistry (IHC) in tumor tissues from nude mice also showed reduced SIRT1 expression upon TIMELESS knockdown." (PMID 38178094, 2024). "In OS, SIRT1 exhibits both tumor-suppressive and oncogenic roles, while Nrf2 is linked to OS progression and activation of OS-supportive anabolic metabolism." (PMID 39852136, 2024). "DACT3-AS1, functioning as a tumor suppressor and exhibiting low expression in CAFs, fosters ferroptosis and enhances tumor cell sensitivity to oxaliplatin via the DACT3-AS1/miR-181a-5p/SIRT1 pathway." (PMID 39717771, 2024). "Aspirin has been reported to inhibit the acetyltransferase activity of P300 and SIRT1, contributing to its anti-tumor activity." (PMID 39598398, 2024). "Targeted delivery of DTX and sirtuin‐1 (SIRT1)‐shRNA by liposomes leads to a significant decrease in tumor burden." (PMID 38919334, 2024). "Quantification of SIRT1 protein levels in the TMAs revealed a high trend towards a decrease in metastases compared with stage II primary tumours (P = 0.070)." (PMID 39494323, 2024). "SIRT1 plays important roles in cell survival, apoptosis, tumor occurrence and development, anti-aging, and metabolic diseases." (PMID 39727955, 2024). "Applying this grouping, patients exhibiting a tumor expressing high levels of Sirt1 had lower OS and lower PFS." (PMID 38427808, 2024). "In this context, future studies should examine xenograft tumours of SIRT1 KO HCT 116 cells exposed to 1,25(OH)2D3." (PMID 39494323, 2024). "During migration, they keep maturing and expressing different markers as seen with an increase in SIRT1 expression when they reach the tumor site." (PMID 39763643, 2024). "The results showed that, compared to the sh-NC group, the tumor volume and weight in the sh-SIRT1 group were significantly reduced, while in the oe-SIRT1 group, the tumor volume and weight were significantly increased compared to the oe-NC group." (PMID 39266959, 2024). "As a tumor suppressor gene, Sirt1 has crucial roles in maintaining heterochromatin structure by deacetylating histones and in regulating Rad5, 1γH2AX, Brca1, and NBS1 foci formation, which are involved in cell cycle checkpoints and DNA damage repair." (PMID 39313797, 2024). "Treatment with MHY2245 significantly reduced colony formation in SKOV3 cells compared to the controls, suggesting that SIRT1 enhances tumor formation and promotes expression of cell-cycle-related genes." (PMID 39272943, 2024). "Among overall CRC patients, MEG3 rs941576 was associated with lymph node (LN) metastasis and tumor stage, serum MEG3 was negatively correlated with tumor stage, while SIRT1 was correlated with the anatomical site." (PMID 38704452, 2024). "The SIRT1/AMPK axis has been studied across different tumor types, influencing tumorigenesis progression." (PMID 39403142, 2024). "DACT3-AS1 inhibits cell proliferation, migration, and invasion by mediating ferroptosis through the miR-181a-5p/SIRT1 axis, enhancing sensitivity of tumor cells to oxaliplatin." (PMID 39703839, 2024).